LINC02985 (long independently transcribed non-coding RNA 2985)
Synonyms: AC156455.1
Gene: Long non-coding RNA gene on chromosome 12 (122,063,214 to 122,068,786, forward strand). Ensembl gene ENSG00000256546.
Diseases named in the same sentence as LINC02985 in open-access papers:
LINC02985 is named in the same sentence as 1 disease in open-access papers, as found by Europe PMC text mining. Sharing a sentence is not in itself a finding about the gene and the disease.
LINC02985 shares sentences with these, for which no sentence is quoted: colorectal cancer (1 paper).